BRCA1 (BRCA1 DNA repair associated)
Diseases named in the same sentence as BRCA1 in open-access papers (continued):
Sharing a sentence is not in itself a finding about the gene and the disease.
tumor (continued). "Because error-free HR is impaired in BRCA1- and BRCA2-deficient cells, it is likely that error-prone repair of HR substrates are causal for the mutations observed in these tumours." (PMID 32680986, 2020). "In line with large-scale network rewiring events, we combined the BRCA1 regulatory network with patient tumor-to-normal differential expression profiles to measure the regulatory potential of BRCA1 in each patient." (PMID 32615918, 2020). "In conclusion, our study suggests that BRCA1 expression is significantly correlated with an advanced tumour grade and stage." (PMID 32334465, 2020). "Using tumor cells deficient for BARD1, a subunit of the BRCA1/BARD1 tumor suppressor complex, we have developed a new orthotopic model of triple‐negative breast cancer that spontaneously metastasizes to the lung and leads to systemic muscle deterioration." (PMID 32730698, 2020). "Long non-coding RNA NBR2 is a transcript of the neighbor of BRCA1 gene 2 and can regulate tumor development." (PMID 32596161, 2020). "RT-PCR analysis further validated that the Brca1-related miRNA miR-212-3p is indeed differently expressed between the control and tumor samples." (PMID 32842712, 2020). "The BRCA1/2 genes are part of the granin gene family and function as tumor suppressors; they play critical roles in maintaining genome stability through controlling pathways involved in DNA damage response/repair, cell cycle and transcription." (PMID 32391281, 2020). "For BRCA1 carriers, the grade of the tumor decreased with increasing age, as well as the proportion of estrogen receptor-negative tumors." (PMID 32481735, 2020). "It is worth noting that HER2-positive breast cancers are mutually exclusive with breast tumours carrying mutations in BRCA1, which is consistent with the incompatibility of overexpressed CDK12 during the genesis of HR-defective tumours." (PMID 34316683, 2020). "BRCA1 and BRCA2 are tumor suppressor genes that encode for proteins that maintain genomic stability through DNA repair." (PMID 32610620, 2020). "Most of the mutations at the amino or carboxy terminus of the protein result in the destruction of zinc finger structures or BRCT repeats, and these two structures play an important role in the tumor suppressor function of BRCA1." (PMID 32356124, 2020). "It is well known that the tumor suppressor genes BRCA1 and BRCA2 play a critical role in homologous recombination, which is considered to be the major mechanism for genome integrity in the process of cell proliferation." (PMID 32879886, 2020). "BRCA1 plays an important role in DNA repair and maintaining genomic stability, and it can also acts as tumor suppressor." (PMID 32587640, 2020). "Due to the alteration of BRCA1 and BRCA2 proteins in tumor cells, BRCA-mutated cells are unable to properly repair double-strand breaks, classically induced by DNA-alkylating agents." (PMID 33302444, 2020). "We compared the tumor microenvironment, immune cells, immune checkpoint molecules, TMB, BRCA1/2 mutation, prognosis, gene ontology, and pathways." (PMID 33282564, 2020). "One HRD tumor carried a pathogenic variant in BRCA2 with LOH of the wild-type allele (case 43), while BRCA1 promoter hypermethylation was observed in another HRD tumor (case 49)." (PMID 33003546, 2020). "A total of 11842 cells were sequenced from all three tumor types and after rigorous quality control filtering, 9983 cells (4154, 3545 and 2284 cells for Neu, PyMT and BRCA1-null tumors, respectively) were retained for subsequent analyses." (PMID 32840210, 2020). "In the SG-resistant, BRCA1/2-wildtype MDA-MB-231 TNBC tumor line, several HRR proteins were found to be upregulated upon SG exposure, among them ERCC1 and Rad51." (PMID 33196706, 2020).
tumor (continued). "Therefore, Brca1 deficiency is a double-edged sword, i.e., genome instability dysregulates massive tumour suppressor and oncogenic factors to promote tumourigenesis, but too much DNA damage initiates a lethal block by inducing apoptosis to retard tumour formation." (PMID 32591500, 2020). "To establish in vitro and in vivo models for the study of the cooperation between BRCA1-KO tumor cells and the stromal compartment, we transduced CST cells with lentiviral plasmids encoding GFP (CST-GFP) or mCherry (CST-mCh)." (PMID 32053991, 2020). "BRCA1 is a tumour suppressor with several genomic functions that maintain genome integrity, including DNA repair and chromatin remodelling." (PMID 33212987, 2020). "The distribution of the tumor characteristics of BRCA1 and BRCA2 carriers agreed with previous reports, so that small, high-grade, and early-onset tumors had a relatively high frequency." (PMID 32964118, 2020). "Id4, a member of the Id (inhibitor of DNA binding) family of proteins, has been demonstrated to downregulate the expression of BRCA1 in in vitro and in-patient tumor samples." (PMID 32235500, 2020). "PIN1 is inhibited by BRCA-1, the tumor suppressor gene suggesting that PIN1 would play an important role in the development of tumors in which BRCA1 is mutated." (PMID 32655497, 2020). "An additional contribution in solving this conundrum is our finding in the Brca1-centered gene-miRNA-protein network that miR-212-3p is simultaneously down-regulated in tumor-colonized samples, which we validated by RT-PCR." (PMID 32842712, 2020). "This suggests that BRCA1 hypermethylation is an early event in tumor development and that tumor progression proceeds along pathways common with BRCA1 germline mutated cases." (PMID 32719340, 2020). "We found that Neu, PyMT and BRCA1-null tumor cell clusters overlapped with distinct normal MEC clusters through this analysis." (PMID 32840210, 2020). "We attempted to call CNVs from our scWES data using this principle and investigated the premalignant changes in Brca1-MT mammary epithelial cells and tumor cells." (PMID 32978388, 2020). "A tissue microarray containing samples from normal and tumor tissue was prepared and stained for BRCA1 protein expression using a commercially available monoclonal antibody against BRCA1 (Ab-1) clone MS110 (mAb)." (PMID 32856871, 2020). "Here, we have further elucidated the pol β bypass of an 8-oxoG at the CpG dinucleotides in the unique DNA sequences of the tumor suppressor BRCA1 gene." (PMID 31963223, 2020). "The capacity for bisphenols to predispose to breast tumorigenesis finds support in the evidence that BPA induces proliferation and hypermethylation of BRCA1 in human non-tumor mammary epithelial cells (HMEC)." (PMID 33330580, 2020). "In agreement with this idea, BRCA1 BRCT mutant mice (Brca1S1598F/S1598F) can survive, have HR deficiency, but appear normal before tumor onset." (PMID 32139898, 2020). "It is possible that Cluster BRCA1-3 cells were also trans-differentiated mesenchymal tumor cells because they were mutually exclusive from cells that had normal copy number variation (CNV) predictions." (PMID 32840210, 2020). "One of these variants is the c.994C>T in the BRCA1 gene, which is described in ClinVar (ID 55775) as a VUS and was detected in the tumor sample with a VAF of 19%, which is relatively low for a germline variant." (PMID 32850417, 2020). "Several studies have suggested that the synthetically lethal interaction between BRCA1 and PARP inhibition is due to the upregulation of NHEJ activity in HR-deficient tumor cells." (PMID 33015058, 2020). "Nevertheless, a pro-tumor role of BRCA1 in TME in the early occurrence of liver metastases cannot be discarded." (PMID 32842712, 2020).
tumor (continued). "Secondly, our study also demonstrated that the promoter methylation of BRCA1 gene is most common in tumor stage II (n= 22/30) and also relates to stage III (n= 8/30)." (PMID 32856871, 2020). "Again, higher BRCA1 promoter methylation levels were found in blood DNA from patients with BRCA1 tumor hypermethylation (t-test, p = 0.005, Wilcoxon’s test, p = 0.01)." (PMID 32719340, 2020). "The BRCA1-null tumors had larger proportions of claudin-low and basal-like tumor cells, whereas Neu and PyMT tumors contained more luminal A and normal-like subtype cells." (PMID 32840210, 2020). "The restoration of BRCA1 expression in the basal SUM1315 cell line seemed to be sufficient to reduce the migration capacity of this tumor cell line." (PMID 33162807, 2020). "In this study, we performed qualitative and quantitative methodology to assess the BRCA1 methylation status in 153 tumor samples." (PMID 32235500, 2020). "Here we assessed stathmin in relation to tumour proliferation, vascular and immune responses, BRCA1 germline status, basal-like differentiation, clinico-pathologic features, and survival." (PMID 32076022, 2020). "BRCA1/2 mutations are one of the basic genetic features of TNBC associated with a deleterious prognosis and sensitization of tumor cells to PARP inhibitors and platinum-based chemotherapy." (PMID 33324554, 2020). "So, the net result of an AhR-induced BRCA1 inhibition is the stimulation of aromatase and E2 (estradiol) increase in tumor cells, which sustains cell proliferation." (PMID 32722276, 2020). "It was suggested that an adjusted targeted capture-based enrichment protocol was superior to commonly applied multiplex PCR-based protocols for reliable BRCA1/2 variant detection, including CNV detection, using FFPE tumor samples." (PMID 32211327, 2020). "The tumor suppressor BRCA1 plays an important role in determining the pathway choice of repair by participating in end resection and promoting HR mediated DSB repair." (PMID 32251466, 2020). "A new national universal tumor BRCA1/2 workflow was approved to support treatment choice, however no strategy is available on the proper handling of BRCA hypermethylated cases with respect to PARPi therapy." (PMID 33352687, 2020). "LOH was evaluated in patients with BRCA1 or BRCA2 germline pathogenic variants (n = 11 for BRCA1; n = 6 for BRCA2) and VUS (n = 1 for BRCA1; n = 7 for BRCA2) in the tumor samples." (PMID 32850417, 2020). "Here, we evaluated the impact of normal physiological glucose on these tumour suppressive roles of BRCA1." (PMID 33212987, 2020). "It is also worth noting that a spectrum of BRCA1-null tumor cells can be found distributed between clusters C12:Bsl and C10:AvP-G." (PMID 32840210, 2020). "The BRCA1 (chromosome 17q21) and BRCA2 (chromosome 13q12.3) are tumor suppressor genes that encode for proteins essential in DNA double strand break repair by homologous recombination (HR)." (PMID 33233347, 2020). "Similar to BRCA1/2, in cases where pathogenic mutations in RAD51C sensitize tumours to PARP inhibition, resistance mechanisms via the acquisition of secondary mutations have been reported." (PMID 36046263, 2020). "Accordingly, BRCA1-null tumor cells exhibited the lowest DPT, PyMT tumor cells had moderate DPT, whereas Neu tumor cells were associated with the highest DPT." (PMID 32840210, 2020). "(A,C,E) t-SNE plots for individual tumor samples (A) BRCA1-null tumor, (C) PyMT tumor and (E) Neu tumor, respectively." (PMID 32840210, 2020). "One large study (n = 577) combined tumours containing hypermethylated BRCA1 promoters with BRCA1 carriers." (PMID 33081408, 2020).
tumor (continued). "BRCA1/BRCA2 tumor testing by next-generation sequencing (NGS) can detect simultaneously both somatic and germline variants, allowing the identification of more patients with higher likelihood of benefiting from PARPi." (PMID 32850417, 2020). "The BARD1 gene is located on chromosome 2q35 and encodes a protein that interacts with the N-terminal region of BRCA1 and acts as a tumor suppressor creating a BRCA1/BARD1 heterodimer with ubiquitin E3 ligase activity." (PMID 32046255, 2020). "Originally identified as an interacting partner of the BRCA1 tumor suppressor, BAP1 augments tumor suppressor functions but has not been identified as a DUB for BRCA1." (PMID 32549302, 2020). "A BRCA mutation is a mutation in either the BRCA1 or BRCA2 gene, both of which are tumor-suppressor genes." (PMID 33019612, 2020). "For example, increased autophagy in BRCA1/2 mutant or dysfunctional tumor cells destabilizes the immunological synapse between cytolytic immune cells and their targets, consequently disrupting transfer of cytotoxic molecules." (PMID 33409454, 2020). "BAP1 belongs to a subfamily of deubiquitinating enzymes that removes ubiquitin from proteins and is a tumor suppressor of BRCA1." (PMID 32101552, 2020). "The expression of 51 genes was able to accurately segregate the three tumour genotypes (BRCA1, BRCA2 and sporadic)." (PMID 33081408, 2020). "(B,D,F) Tables summarizing the sub-clusters, putative identities and key cluster defining genes; (B) BRCA1-null tumor, (D) PyMT tumor and (F) Neu tumor, respectively." (PMID 32840210, 2020). "Since their discovery in 1994 and 1995 respectively, there has been significant clinical interest in the tumor suppressor genes BRCA1 and BRCA2, with particular focus in recent years on targeted therapies for patients with BRCA mutated cancers." (PMID 32493233, 2020). "In the tumor microenvironment, the tumor suppressor gene BRCA1 activates NRF2, whereas the oncogene Fyn mediates nuclear export and induces degradation of NRF2." (PMID 32849814, 2020). "BRCA1 functions as a tumor suppressor due to its role in the maintenance of genomic stability via its multiple roles in the cellular response to DNA double-strand breaks (DSBs, see next sections)." (PMID 32013256, 2020). "The data suggest that blocking excessive inflammasome activity in Brca1 mutant tumor can postpone tumor recurrence and inhibit tumor metastasis through impaired the recruitment of TAMs." (PMID 32195105, 2020). "The BARD1 protein is a RING heterodimer that interacts with BRCA1, providing the E3 ubiquitin ligase activity that is required for BRCA1’s tumor suppressor function, as well as coordination of ubiquitination to maintain genomic stability." (PMID 32085533, 2020). "The presence of mesenchymal populations in BRCA1-null tumors was also concordant with the assignment of claudin-low subtypes in this tumor type." (PMID 32840210, 2020). "The mutational signatures and chromosomal instability markers of HR deficiency have been aggregated into the HRDetect score, robustly identifying BRCA1/2 tumours with potential greater accuracy than indexes such as HRD-score." (PMID 32471999, 2020). "In this review, we focus on the function of BARD1 in centrosome regulation and its role as a tumor suppressor together with BRCA1/OLA1/RACK1." (PMID 32722046, 2020). "BRCA1 was also described as a protector factor in fibroblast exposed to tumor factors avoiding cell malignancy." (PMID 32842712, 2020). "Cells from cluster BRCA1-3 were classified as tumor because they were predicted to harbor chromosomal amplification or deletion events." (PMID 32840210, 2020). "Different BRCA1 functions can lead to its tumour suppression activity; include DNA repair roles,cell cycle control and transcriptional regulation." (PMID 34803264, 2020).
tumor (continued). "Risk score, tumor size, CDKN2A mutation, BRCA1 mutation, N stage, residual tumor, history of radiation therapy, targeted molecular therapy, and chemotherapy were identified to be significantly related to OS of PDAC in univariate Cox analysis, with p < 0.05." (PMID 33033514, 2020). "A significant relation between BRCA1 expression and advanced tumour stage was found which coincides with the reports from other researches." (PMID 32334465, 2020). "BRCA1 carriers were largely (74%) basal-like, while tumours from BRCA2 carriers and BRCAx were largely (73% and 60%) luminal, an observation which has also been observed in subsequent studies." (PMID 33081408, 2020). "In particular, BAP1 is thought to bind to the breast cancer type 1 susceptibility protein (BRCA1) and the BRCA1-associated RING domain protein 1 (BARD1) and enhance their tumor suppressor function." (PMID 32226777, 2020). "These three TNBC tumor models, PDX-110 (BRCA1-mutated), PDX-322, and PDX-744 were derived from samples taken at the time of surgery from drug-naïve patients." (PMID 30770823, 2019). "Knocking-down BRCA1 also significantly (p < 0.0001) increased ALDH+ population in the siBRCA1-treated tumor cells." (PMID 31273285, 2019). "Proteins encoded by these three tumor susceptibility genes (PALB2, BRCA1, BRCA2) cooperate in the BRCA pathway by forming a complex, which is essential for HR repair." (PMID 31877165, 2019). "Low BRCA1 results in hypermutation in tumor cells and generates more somatic alterations in DNA and protein sequences with antigen potential." (PMID 31023256, 2019). "Consistent with our previous findings, hypoxia, the hallmark of tumor microenvironment, significantly increases the CSC-like population in both BRCA1-deficient and -competent HCC1937 cells." (PMID 31273285, 2019). "KLF4 and BRCA1 exhibited stronger staining in tumor tissues of immunodeficient mice injected with A2780 scramble cells than the mice injected with A2780 sh-circPLEKHM3 cells." (PMID 31623606, 2019). "Grade 3 was the most common tumor grade in BRCA1 tumors (65%), followed by BRCA2 (44%) tumors, compared to only 27% of BRCA WT tumors (p < 0.001, p = 0.006, respectively)." (PMID 31307407, 2019). "We found broadly consistent associations of height in both BRCA1 and BRCA2 mutation carriers by menopausal status and by tumour histological type and grade." (PMID 31213659, 2019). "In the tumor microenvironment, activation of Nrf2 is promoted by the tumor suppressor genes BRCA1 and protein p21 and is blocked by Fyn-mediated degradation." (PMID 31546975, 2019). "The interaction between BARD1 and BRCA1 promotes tumor suppressor functions by acting in double-strand break repair and apoptosis initiation." (PMID 31036035, 2019). "Conceptually, our findings strongly suggest that a direct role of BRCA1 in chromatin reorganization and transcriptional regulation contributes to its tissue-specific tumor suppressor function." (PMID 30995943, 2019). "Given the discrepancy of the results from the two studies, the implication of BRCA1 E3 ligase activity in tumor suppression remains to be elucidated." (PMID 30696104, 2019). "Whole body deletion of the mouse Palb2 gene results in early embryonic lethality similarly to the Brca1 and Brca2 knock-out animals, indicating that all three tumor suppressor gene products, Palb2, Brca1 and Brca2 are essential for embryonic viability." (PMID 31877165, 2019). "ER status was also the only independent tumor characteristic that distinguished between BRCA1 and BRCA2 carriers (ORBRCA2 vs BRCA1: 0.22 [0.07–0.77])." (PMID 30175445, 2019).